INS (insulin)
Diseases named in the same sentence as INS in open-access papers (continued):
Sharing a sentence is not in itself a finding about the gene and the disease.
Hepatic steatosis (continued). "In experimental high-fat diet models, renal and hepatic sympathetic denervation reduced hepatic insulin resistance, decreased hepatic glucose production, and reversed hepatic steatosis." (PMID 41517385, 2025). "In animal models, the administration of FGF19 and FGF21 decreases body weight and lipid mass and improves insulin sensitivity, hepatic steatosis, and serum lipid levels." (PMID 40565181, 2025). "Out of the 12 RCTs that were included in the study, there was a significant reduction in hepatic steatosis, an increase in insulin sensitivity, and a decrease in inflammatory markers." (PMID 40525060, 2025). "Hepatic steatosis, when present for a prolonged duration, leads to changes in lipid metabolism, increased hepatic glucose production, and blunted insulin signaling, ultimately contributing to metabolic deterioration." (PMID 41220583, 2025). "Conversely, moderate exercise consistently demonstrates significant improvements in hepatic steatosis, inflammation, and insulin sensitivity, underscoring the critical role of physical activity in MASLD management." (PMID 41001122, 2025). "Like HuR-deficient mice, liver-specific Pten knockout mice show increased insulin sensitivity but develop more severe hepatic steatosis." (PMID 40809813, 2025). "It has strong antioxidant activity, and several studies have shown that isoquercetin has therapeutic effects on insulin resistance, fat oxidation and hepatic steatosis." (PMID 41573724, 2025). "Specifically, studies using Mgll−/− mice on an HFD diet showed significant improvements in body weights, serum lipid profiles, insulin sensitivity, and hepatic steatosis compared to WT mice." (PMID 40245985, 2025). "Specifically, MASLD-driven overproduction of fetuin-A and selenoprotein P impairs adipose tissue insulin signaling, creating a feedforward loop between hepatic steatosis and systemic IR." (PMID 40458180, 2025). "Within this model, an excessive lipid intake induced hepatic steatosis, while additional carbohydrate supplementation enhanced de novo lipogenesis, increased oxidative burden, and disrupted insulin signaling, ultimately accelerating disease progression." (PMID 41373985, 2025). "Univariate analysis of the occurrence of GDM showed that the risk of GDM was positively associated with BMI, ALT, TG, insulin, HOMA-IR, and hepatic steatosis and negatively associated with HDL and AST/ALT ratio." (PMID 40880520, 2025). "A low-carbohydrate diet reduces hepatic steatosis by decreasing insulin levels, enhancing lipolysis and fat oxidation, and diminishing de novo lipogenesis." (PMID 41335609, 2025). "Univariate analyses revealed that elevated levels of HOMA-IR, pre-pregnancy BMI, TG, FPG, insulin, GGT, ALT, and grades of hepatic steatosis were significantly associated with an increased GDM risk, while HDL showed an inverse relationship." (PMID 39962434, 2025). "Liraglutide (a long-acting GLP-1 analogue) and semaglutide (a GLP-1 receptor agonist) have been confirmed by clinical controlled trials to slow hepatic steatosis and non-alcoholic steatohepatitis, in addition to affecting insulin release." (PMID 41244044, 2025). "Studies show that various forms of exercise enhance insulin signaling, improve glucose tolerance, and reduce liver steatosis in animal models." (PMID 40522819, 2025). "Liver fat accumulation, a key feature of hepatic steatosis, impairs hepatic insulin sensitivity and triggers systemic inflammation, contributing to glucose dysregulation." (PMID 40551893, 2025). "While direct evidence of FuFAs’ impact on hepatic steatosis is limited, they appear to reduce liver fat accumulation through their insulin-sensitizing effects." (PMID 40292496, 2025). "In preclinical models, even at low doses, DNP improved hepatic steatosis, lowered fasting glucose and insulin levels, and reduced triacylglycerol content in liver, plasma, and skeletal muscle in high-fat-fed rats." (PMID 40869061, 2025).
Hepatic steatosis (continued). "The disorder amplifies systemically as insulin-resistant adipose tissue increases lipolysis, flooding the liver with additional FFAs and further exacerbating hepatic steatosis and inflammation." (PMID 41244044, 2025). "Retatrutide has shown the potential to reduce hepatic steatosis, accompanied by changes in adiponectin, leptin, triglycerides, and FGF21 levels—factors closely associated with lipid metabolism and insulin sensitivity." (PMID 40243565, 2025). "Adherence to the MD, as evaluated by the MedDietScore, was negatively correlated with serum levels of liver damage parameters, severity of liver steatosis, and insulin levels." (PMID 39851512, 2025). "Reduces body weight, decreases visceral fat mass, improves serum lipid profile (reduces cholesterol, NEFA, TNF-α), decreases liver lipid accumulation, improves hepatic steatosis, and lowers insulin levels." (PMID 39963239, 2025). "It improves glycemic control independently of insulin signaling and ameliorates hepatic steatosis in preclinical models." (PMID 40869061, 2025). "This causes hepatic steatosis, a feature of MASLD, which in turn affects insulin signaling and thus induces insulin resistance." (PMID 41220583, 2025). "Inhibiting hepatic gluconeogenesis and increasing hepatic glycogen synthesis, elevating serum insulin levels, and suppressing hepatic steatosis." (PMID 41189619, 2025). "This study examined how adherence to the MIND diet relates to MASLD severity, focusing on hepatic steatosis, fibrosis, insulin resistance, inflammation, and gut microbiota diversity." (PMID 40927568, 2025). "FGF21 also reduces hepatic steatosis by inhibiting lipogenesis and increasing energy expenditure, insulin sensitivity." (PMID 40301996, 2025). "HIIT was more effective in enhancing insulin sensitivity, ameliorating hepatic steatosis, reducing adipocyte hypertrophy." (PMID 40305497, 2025). "In these patients, particularly those with metabolic dysfunction-associated steatotic liver disease, physical exercise improves insulin sensitivity and hepatic steatosis." (PMID 41551595, 2025). "We’ve shown in previous studies that antibody-mediated neutralization of FABP4 improves metabolic health in obese mice by lowering hepatic glucose production, improving insulin sensitivity, and reducing hepatic steatosis." (PMID 39843629, 2025). "Piperine has many pharmacological effects and several health benefits, especially against chronic diseases, such as increased insulin sensitivity, anti-inflammatory effects, and improvement of hepatic steatosis." (PMID 40003964, 2025). "In pre-clinical studies, the genetic disruption or antisense-mediated knockdown of STK25 in animal models has shown significant reductions in liver steatosis and improved insulin sensitivity." (PMID 40004240, 2025). "BHB plays a significant role in managing alcoholic fatty liver and early cirrhosis by improving insulin sensitivity, reducing hepatic fat accumulation, and providing antioxidant protection against oxidative stress." (PMID 41502820, 2025). "This reduced hepatic steatosis correlates with preserved hepatic insulin sensitivity and more favorable glucose and lipid metabolisms." (PMID 41008585, 2025). "Its role in glucose metabolism involves both potentiation of glucose-stimulated insulin secretion via pancreatic TrkB receptors and enhancement of peripheral insulin sensitivity, collectively ameliorating hepatic steatosis." (PMID 41488134, 2025). "CAP-fed wild-type (WT) mice showed reduced hepatic steatosis, improved lipid profiles, enhanced insulin sensitivity, and suppressed hepatic inflammation." (PMID 40864772, 2025). "In hepatic steatosis, the hepatic glucose utilization rate is increased, possibly as a result of IR and elevated insulin levels in the bloodstream." (PMID 39138826, 2025).
Hepatic steatosis (continued). "In this case, the switch from liraglutide to tirzepatide demonstrated an improvement in HbA1c with a reduction in the daily insulin dose and showed amelioration of the hepatic steatosis and fibrosis in the histological evaluations." (PMID 40491599, 2025). "A novel synthetic verbenone derivative, SP-1154, significantly improved insulin sensitivity and glucose homeostasis, and reduced hepatic steatosis in the NAFLD mouse model." (PMID 40002806, 2025). "This reduced hepatic steatosis correlates with preserved hepatic insulin sensitivity and more favorable glucose and lipid metabolism." (PMID 41008585, 2025). "Fiber and fructans (inulin and fructooligosaccharides) enhance insulin sensitivity and reduce hepatic steatosis, while anthocyanins and polyphenols support lipid metabolism and mitigate oxidative stress." (PMID 41009545, 2025). "Post-mortem analyses included qPCR, Western Blotting, biochemical and microscopical assessments for hepatic steatosis and insulin resistance, hypothalamic and adipose tissue inflammation, and circulating lipid, leptin and IL-6 levels." (PMID 39754229, 2025). "Ipragliflozin reduces hepatic steatosis, hyperlipidemia, oxidative stress, and improves insulin sensitivity." (PMID 40004240, 2025). "FGF21 has been reported to promote glucose uptake in adipose tissue, increase insulin secretion, improve insulin sensitivity, and reverse hepatic steatosis." (PMID 40149860, 2025). "Biologically, the combination of visceral adiposity with excess saturated fat intake and low micronutrient density provides a plausible mechanistic pathway through insulin resistance and hepatic steatosis." (PMID 41228471, 2025). "These antidiabetic agents regulate blood glucose through various mechanisms, such as improving insulin sensitivity, promoting insulin secretion, and delaying gastric emptying, while also reducing the severity of fatty liver." (PMID 41573193, 2025). "For instance, fungal metabolites (enzymatic derivatives, alcohol) enhance intestinal lipid absorption, accelerate hepatic steatosis, and trigger systemic insulin resistance." (PMID 41140404, 2025). "Deleting dihydroceramide desaturase 1 (DES1) in the liver resolved hepatic steatosis and improved insulin sensitivity in diet-induced obese mice by increasing the dihydroceramide (DCER) levels that decreased ceramide species with a critical double bond." (PMID 40564914, 2025). "Fructose intake induced an increase in proinflammatory cytokines in portal plasma, liver, and skeletal muscle, a decrease in insulin sensitivity in both tissues and a condition of hepatic steatosis." (PMID 40207597, 2025). "In patients with chronic liver disease, particularly those with metabolic dysfunction-associated steatotic liver disease (MASLD), physical exercise improves insulin sensitivity and hepatic steatosis." (PMID 41551595, 2025). "Previous work has established that the Mediterranean Diet reduces liver steatosis, improves insulin sensitivity, reduces the severity of liver disease and reduces the likelihood of MASH in adults with MASLD." (PMID 40362724, 2025). "The primary phenotypic targets of empagliflozin include reducing liver steatosis and fibrosis, improving insulin sensitivity, and decreasing hepatic triacylglycerol levels." (PMID 40004240, 2025). "miR-33a/b is involved in fatty liver disease and participates in lipid transport and metabolism by targeting some genes that have roles in insulin signaling pathways and in cholesterol homeostasis." (PMID 41226441, 2025). "The new name definitively reveals the pathophysiology of fatty liver with metabolic dysfunction and insulin resistance." (PMID 40104566, 2025). "The transition from hepatic steatosis to MASH and advanced fibrosis involves a complex interaction of pathogenic factors, including insulin resistance and the buildup of harmful lipid intermediates that cause hepatocellular damage and fibrogenesis." (PMID 40867807, 2025).
Hepatic steatosis (continued). "Mice modified to express miR-30a at elevated levels in adipose tissues maintain insulin sensitivity coupled with reduced fatty liver disease when fed a high-fat diet." (PMID 40471675, 2025). "Rapamycin, a well-known mTORC1 inhibitor, has been shown to decrease liver fat accumulation, lower serum alanine aminotransferase (ALT) levels, and improve insulin sensitivity in mouse models of fatty liver disease." (PMID 40867807, 2025). "We have previously showed insulin signaling as a potential natural killer cell checkpoint in fatty liver disease." (PMID 40643462, 2025). "In MASLD, PA improves insulin sensitivity, reduces visceral fat, and enhances lipid metabolism, which helps mitigate hepatic steatosis." (PMID 39845917, 2024). "This relative insulin-resistant state can affect glucose and lipid hepatic metabolism, triggering pro-inflammatory cascades and resulting in hepatic steatosis, fibrosis, and cirrhosis." (PMID 38681765, 2024). "They improve insulin sensitivity, which is crucial for managing NAFLD, as enhanced insulin sensitivity helps mitigate the risk of hepatic steatosis." (PMID 39377405, 2024). "Omega-3 PUFAs show beneficial effects via a reduction in the inflammatory response and oxidative stress and improvement of insulin sensitivity and therefore can decrease hepatic steatosis." (PMID 39609906, 2024). "We evaluated the effects of diet treatments on fat distribution, glucose, and insulin homeostasis as well as hepatic steatosis." (PMID 38577162, 2024). "As a result, metformin treatment would alleviate hepatic steatosis, thereby enhancing insulin sensitivity and, consequently, insulin’s ability to inhibit gluconeogenesis." (PMID 38785784, 2024). "Further studies at the NIH and other treatment centers showed that metreleptin decreased hyperphagia, improved insulin sensitivity, reduced liver steatosis and improved NASH score on biopsy specimens." (PMID 38952397, 2024). "Resolvin D3 ameliorates ER stress through AMPK-regulated autophagy signaling, thereby attenuating skeletal muscle insulin resistance and hepatic steatosis in obese mice." (PMID 38195611, 2024). "Aerobic and resistance exercise for 4 months in randomized controlled trials in inactive people with T2D and MASLD improved insulin sensitivity, and reduced liver steatosis and the hepatic fat content." (PMID 38891759, 2024). "Here, we conducted a series of metabolic studies under four distinct dietary conditions to assess the impact of liver-specific Agpat5 deletion on plasma insulin levels, glucose tolerance, plasma cholesterol levels, and hepatic steatosis." (PMID 39608054, 2024). "C16:0 and C14:0 feeding elicits increases in BW, reduced insulin secretion, hepatic steatosis, and increased endoplasmic reticulum stress in mouse adipose tissue and insulin-secreting INS-1E cells." (PMID 39272602, 2024). "It has been shown that the Mediterranean diet reduces hepatic steatosis and improves insulin sensitivity in an insulin-resistant NAFLD population compared to current dietary recommendations, even without weight loss." (PMID 38999744, 2024). "It seems that the relationship between inflammation and hepatic steatosis is profoundly influenced by insulin resistance." (PMID 38589782, 2024). "In the present study, we evaluated the effect of 12 weeks of KD on fat mass distribution, glucose and insulin tolerance, hepatic steatosis, lipid metabolism and inflammatory profile in mice." (PMID 38577162, 2024). "Liver-specific knockdown of Fatp2 using shRNA improved high-fat diet-induced hepatic steatosis and increased insulin sensitivity in mice." (PMID 39850557, 2024). "In the context of reduced hepatic steatosis and adipose tissue macrophage infiltration, Trib3 KO mice maintained lower circulating insulin levels and exhibited increased insulin-dependent skeletal muscle glucose uptake than did control mice." (PMID 39623091, 2024).
Hepatic steatosis (continued). "While the full NAFLD pathogenesis remains elusive, insulin resistance is considered a core mechanism in hepatic steatosis." (PMID 38509247, 2024). "The men younger than 55 years had higher central adiposity, glucose, insulin resistance, transaminases and blood pressure than the women, who, in turn, presented with more hepatic steatosis (measured by HSI) and a higher ALT/AST ratio." (PMID 39767255, 2024). "The HSI has been accepted as a simple, efficient and noninvasive tool to assess hepatic steatosis, being correlated with insulin resistance." (PMID 39767255, 2024). "Mouse experiments indicated that theobromine treatment notably decreased liver steatosis, reduced lipid accumulation, lowered blood lipid levels, and enhanced insulin sensitivity." (PMID 38839921, 2024). "According to the results of the present study, it can be said that the supplementation of GSE for 2 months can be effective in improving the lipid profile, insulin resistance, blood pressure, and the severity of hepatic steatosis in patients with NAFLD." (PMID 38755622, 2024). "This was associated with a severe reduction in adipokine levels, massive liver steatosis, dramatic elevation of glucose and insulin levels, and extreme insulin resistance." (PMID 38727299, 2024). "Blocking the IKK ɛ and TBK1 pathways can significantly reduce the inflammatory factors produced by pro-inflammatory cells such as TNF- α and MCP-1, thereby improving insulin sensitivity and reducing liver steatosis." (PMID 38436022, 2024). "Knockout of miR-34a in HFD-fed obese mice attenuated VAT fibrosis, local (WAT CLS formation/M1 polarization) and systemic (serum cytokines: TNF-α, IL-6, IL-1β, and MCP-1) metaflammation, insulin resistance, and hepatic steatosis." (PMID 39063184, 2024). "Intermittent osteocalcin injections have been shown to increase glucose tolerance and insulin sensitivity, improve pancreatic β-cell mass, and prevent hepatic steatosis in mice." (PMID 39872315, 2024). "As hepatic steatosis progresses, cellular injury and impaired insulin signaling within the liver worsen inflammatory processes and promote fibrogenesis." (PMID 39518569, 2024). "Surprisingly, these mice are also protected from liver steatosis and present improved glucose tolerance and insulin sensitivity." (PMID 38470490, 2024). "Several studies have shown that the application of ASBT inhibitors can ameliorate high-fat diet-induced hepatic steatosis, reduce hepatic lipid accumulation, and improve insulin sensitivity in NAFLD mice." (PMID 39850557, 2024). "A previous study demonstrated that gallic acid, contained in GFL, ameliorated hepatic steatosis by normalizing insulin signaling, lipid profile, and liver weight in diabetic rats." (PMID 39796441, 2024). "An additional possibility for the contributions of Them2 to hepatic steatosis and insulin resistance is crosstalk between skeletal muscle and the liver." (PMID 39369989, 2024). "In contrast, overexpression of ANGPTL6 increases insulin sensitivity and energy expenditure and protects against the development of hepatic steatosis." (PMID 39409124, 2024). "In particular, a study reported that mice lacking functional Gi proteins in adipocytes displayed increased lipolysis, resulting in reduced insulin sensitivity and higher hepatic steatosis when maintained on an obesogenic diet." (PMID 38470490, 2024). "Many studies have shown that TRF has beneficial metabolic effects such as improved insulin sensitivity, reduced hepatic steatosis and hyperlipidemia, and amelioration of oxidative stress and inflammation." (PMID 38338668, 2024). "Compared to PUFA, SFA leads to hepatic steatosis by decreasing whole-body oxidation and insulin-mediated inhibition of lipolysis upon entry into the human body, thus increasing hepatic and other visceral fat deposition, as well as weight gain." (PMID 39221157, 2024).